CRHR2 (corticotropin releasing hormone receptor 2)
Diseases named in the same sentence as CRHR2 in open-access papers (continued):
Sharing a sentence is not in itself a finding about the gene and the disease.
colitis (11 papers, 2015 to 2024). Inflammation of the colon. "On the other hand, either Crhr2 encoding gene deletion or CRHR2 inhibitor treatment exacerbates DSS-induced mouse colitis." (PMID 33494263, 2021). "CRHR2 is involved in regulating various cellular events, including mucosal repair in colitis, angiogenesis, and Fas-mediated apoptosis in colon cancer." (PMID 33494263, 2021). "When it comes to the exacerbated tumorigenesis in Crhr2−/− mice tested in the AOM/DSS model, we have previously demonstrated that Crhr2 gene deletion or CRHR2 inhibitor treatment worsens DSS-induced mouse colitis." (PMID 33494263, 2021). "Intriguingly, the administration of UCN1 in male Crhr2 heterozygous mice with colitis ameliorates inflammation and increases survival." (PMID 32244319, 2020). "CRHR1 promotes intestinal inflammation and angiogenesis; in contrast, CRHR2 is antiangiogenic and inhibits inflammation in experimental colitis." (PMID 26839731, 2015). "Selective inhibition of CRHR2 signaling in experimental colitis mice could promote disease activity, destroy the impaired intestinal barrier, increase colonic epithelial cell apoptosis, and decrease epithelial cell proliferation." (PMID 30881446, 2019). "In contrast, CRHR2 signaling enhanced mucosal repair responses after DSS-induced colitis." (PMID 27500935, 2016). "An antagonist of VEGFR2 activity alleviated colitis in CRHR2(−/−) mice." (PMID 26839731, 2015). "In a DSS-induced colitis mouse model, only CRHR1 knockdown decreased microvascular density, via inhibition of VEGF levels, thus suggesting that CRHR1 acts pro-angiogenic, while CRHR2 has anti-angiogenic properties during intestinal inflammation." (PMID 31614860, 2019). "rWAS exposure increased the gene expression levels of IFN-γ, UCN2 and CRHR2 in LI-LPMCs; however, there was no sign of colitis in C57BL/6 mice." (PMID 27500935, 2016). "Characteristically, in a DSS induced colitis murine model, CRHR1 knockdown showed decreased intestinal inflammation, while CRHR2 knockdown exerted increased inflammation, thus supporting the pro-inflammatory and anti-inflammatory roles of CRHR1 and CRHR2 respectively in the intestine." (PMID 31614860, 2019).
Insulin resistance (5 papers, 2018 to 2023). Increased resistance towards insulin, that is, diminished effectiveness of insulin in reducing blood glucose levels. "Overall, this study has important implications for the potential use of CRHR2 antagonists for treatment of insulin resistance and offers insights into the molecular relationship between insulin’s effects and GPCR signal transduction." (PMID 37402735, 2023). "In the current study, acute UCN2 dosing agonizes CRHR2 causing insulin resistance in the skeletal muscle, whereas chronic, elevated levels of UCN2 desensitize CRHR2 leading to the opposite: insulin sensitization." (PMID 37402735, 2023). "The corticotropin-releasing hormone receptor 2 (CRHR2) gene encodes CRHR2, contributing to the hypothalamic–pituitary–adrenal stress response and to hyperglycemia and insulin resistance." (PMID 36077219, 2022). "In Crhr2 null male mice, fat redistribution and dyslipidemia contributed to the development of metabolic phenotype and insulin resistance." (PMID 30400826, 2018). "Enhanced release of glucagon, glycogenolysis, and peripheral insulin resistance may explain hyperglycemia in Crhr2 null mice." (PMID 30400826, 2018). "The circulating levels of UCN2 reported in murine models of insulin resistance and in human patients with increased HOMA-IR fall in the range where we would expect to see mostly Gs recruitment to CRHR2 and very little alternative activation." (PMID 37402735, 2023). "The lack of effect of in vivo CRHR blockade on insulin resistance during pregnancy suggests that the impaired glucose tolerance reflects a β-cell targeted effect, consistent with our in vitro observations of enhanced insulin secretion in response to CRHR2 activation." (PMID 32106091, 2020).
type 2 diabetes (5 papers, 2018 to 2023). "A recent genome-wide association study of approximately 890,000 people with type 2 diabetes (DIAGRAM consortium) identified several novel diabetes susceptibility loci including the stress receptor corticotropin-releasing factor receptor 2 (Crhr2)." (PMID 32244319, 2020). "A drug that modulates skeletal muscle glucose uptake for the treatment of type 2 diabetes could have significant therapeutic impact, and these findings should be considered when determining the effectiveness of targeting CRHR2 or similar GPCRs for this purpose." (PMID 37402735, 2023). "While CRHR2 variants confer risk for mood disorders, MDD, and type 2 diabetes, they have not been investigated in familial T2D and MDD." (PMID 36077219, 2022). "Our findings that only male mice with Crhr2 genotype, but not female mice develop impaired glucose clearance and other metabolic phenotypes on short-term nutritional stress, is in agreement with clinical reports that men are more prone to developing type 2 diabetes under stressful conditions." (PMID 30400826, 2018).
colon cancer (4 papers, 2013 to 2024). "With these two mouse models of colon cancer, our data clearly show that Crhr2 deficiency greatly promotes the development and growth of tumors in the intestine, while worsens disease severity in mice." (PMID 33494263, 2021). "Together, these data suggest that in the mouse model of AOM/DSS-induced colon cancer, Crhr2 deficiency exacerbates tumorigenicity, while loss of Crhr1 does not seem to alter the intestinal tumor development and growth." (PMID 33494263, 2021). "Taken together, these data indicate that loss of the Crhr2 gene promotes tumor formation and growth in the chemically induced model of colon cancer." (PMID 33494263, 2021). "In conclusion, our data clearly suggest that the Crhr1 deficiency confers a tumor-suppressing effect, while the Crhr2 deficiency has the potential to worsen the development and growth of colon cancer." (PMID 33494263, 2021). "Considering these data, it is reasonable to speculate that a pharmacological stimulation of the CRHR2-mediated response would induce tumor-preventive or tumor-suppressive effect in individuals with a risk of colon cancer." (PMID 33494263, 2021). "Our finding is in agreement with the previous study that the CRHR2 mRNA level is lower in human colon cancer tissues compared to normal tissues." (PMID 33494263, 2021). "We found that the mRNA level of CRHR2 was substantially lower in colon cancer tissues than that of normal tissues, while the CRHR1 levels are comparable between these tissues." (PMID 33494263, 2021). "Intriguingly, the level of CRHR2-targeting UCN II was markedly increased in colon cancer tissues compared to that of controls, while NLRC4 levels are preserved." (PMID 33494263, 2021). "Therefore, either antagonists against CRHR1 or pharmacological activation of CRHR2-mediated responses should merit further investigation for developing a novel approach against colon cancer in humans." (PMID 33494263, 2021). "Therefore, pharmacological inhibitors of CRHR1 or activators of CRHR2 could be of significance as anti-colon cancer drugs." (PMID 33494263, 2021). "Thus, we investigate the role of CRHR1 and CRHR2 in colon cancer." (PMID 33494263, 2021). "In this study, we observed that the mRNA levels of CRHR2 and its cognate ligand UCN III are substantially reduced in human colon cancer tissues compared to normal colon tissues." (PMID 33494263, 2021). "It is of interest that in contrast to the reduced expression of CRHR2 and UCN III, the expression of UCN II (another specific ligand of CRHR2) is markedly increased in the colon cancer tissues compared to normal tissues." (PMID 33494263, 2021). "The mRNA levels of CRHR2 and UCN III are reduced in human colon cancer tissues compared to those of normal tissues." (PMID 33494263, 2021). "Furthermore, the mRNA level of UCN III, a CRHR2-specific peptide among the CRH family, was dramatically reduced in colon cancer tissues compared to that of controls; however, the level of CRH, a CRHR1-restricted ligand, was not changed in these tissues." (PMID 33494263, 2021). "Given the reduced expression of CRHR2 and its ligand UCN III in human colon cancer tissues, these findings indicate that the impairment of CRHR2-mediated responses should be associated with colon cancer development in humans, which may contribute to cancer metastasis or poor patient survival." (PMID 33494263, 2021).
colorectal cancer (4 papers, 2013 to 2020). A primary or metastatic malignant neoplasm that affects the colon or rectum. "CRHR2 has been associated with endometriosis, localization of glucose transporters in the placenta, colorectal cancer, stress response in the cortisol pathway, and leptin responsiveness." (PMID 28417008, 2017). "In a previous study, CRHR2 was identified as a gene which contributing to reversal of colorectal cancer cell resistance." (PMID 32812032, 2020).
endometriosis (4 papers, 2013 to 2020). The growth of functional endometrial tissue in anatomic sites outside the uterine body. "Given the fact that we observed an increase in mRNA in both, CRHR1 and CRHR2, in rats with endometriosis that received vehicle, we can infer that catecholamine secretion is also altered due to endometriosis." (PMID 31935235, 2020). "We further compared the expression of CRH, UCN, CRHR1 and CRHR2 in ectopic endometrium to that in eutopic endometrium of women with endometriosis." (PMID 23638035, 2013). "Further mechanistic experiments and experiments on appropriate models needs to be done in order to clarify this role and highlight a potential use of anti-CRHR1 and anti-CRHR2 treatment in endometriosis." (PMID 23638035, 2013). "In the same study, we also showed that CRH R1 and CRHR2 are significantly more expressed by the eutopic endometrium of women with endometriosis compared to the corresponding eutopic endometrium of healthy women, implying an increased CRH effect on the eutopic endometrium of women with endometriosis." (PMID 25473847, 2014). "Interestingly, we found that the expression of CRH, UCN and their receptor subtypes, CRHR1 and CRHR2 is stronger in ectopic endometrium compared to that in eutopic endometrium of women with endometriosis." (PMID 23638035, 2013). "We compared the expression levels of CRHR1 and CRHR2 in eutopic endometrium of endometriotic women with that in eutopic endometrium of healthy women to further examine the implication of these molecules in endometriosis and the infertility profile of endometriotic women." (PMID 23638035, 2013). "CRH, UCN, CRHR1 and CRHR2 mRNA were also more highly expressed in ectopic rather than eutopic endometrium in women with endometriosis." (PMID 25473847, 2014). "Despite the fact that CRH/UCN have been implicated in endometriosis – a fact also verified by our results, no data has been reported so far concerning the expression of CRHR1 and CRHR2, the CRH and UCN receptors." (PMID 23638035, 2013). "This is the first time a study shows that CRHR1 and CRHR2 and specifically the CRHR1β and CRHR2α receptor subtypes are expressed at mRNA and protein level, not only in the endometrium but also at endometriotic sites indicating a potential crucial role of CRH and UCN in endometriosis." (PMID 23638035, 2013). "Unidentified endometrial defects in endometriosis could also affect the expression of CRH and UCN resulting in increased expression of CRHR1 and CRHR2 acting as a regulatory mechanism to compensate for the reduced efficiency of proper endometrial function of endometriotic women." (PMID 23638035, 2013). "CRH, UCN, CRHR1 and CRHR2 mRNA were also more highly expressed in ectopic rather than eutopic endometrium (CRH, UCN, CRHR2α: p<0.01, CRHR1β: p<0.05) and protein (CRH and UCN: p<0.05, CRHR1 and CRHR2: p<0.01) in women with endometriosis." (PMID 23638035, 2013).
Hypertension (4 papers, 2012 to 2024). The presence of chronic increased pressure in the systemic arterial system. "In addition, CRHR2-knockout mice developed high blood pressure, increased feeding, and impaired glucose tolerance, all traits related to T2D and metabolic syndrome." (PMID 36077219, 2022).
metabolic syndrome (4 papers, 2017 to 2022). A cluster of metabolic risk factors for CARDIOVASCULAR DISEASES and TYPE 2 DIABETES MELLITUS. "Female mice of Crhr2 genotype were protected from HFD-induced dyslipidemia." (PMID 30400826, 2018).
post-traumatic stress disorder (4 papers, 2012 to 2022). An anxiety disorder precipitated by an experience of intense fear or horror while exposed to a traumatic (especially life-threatening) event. "Risk variants in the CRHR2 gene have been reported in patients with MDD, bipolar disorder, and post-traumatic stress disorder (PTSD); and one risk variant has been reported in T2D; however, variants in comorbid MDD-T2D patients have not been studied." (PMID 36077219, 2022).
diabetes (3 papers, 2012 to 2020). "For example, disruption of CRHR2 signaling in pancreatic SST-producing cells has been shown to contribute to diabetes development." (PMID 29880854, 2018).
hypercortisolism (3 papers, 2022 to 2024). "However, CRHR1- and CRHR2-risk variants might also lead to hypercortisolism and confer mental-metabolic pleiotropic effects." (PMID 37543650, 2023). "Dysfunctional CRH receptor 1 (CRHR1) and CRH receptor 2 (CRHR2), both of which are involved in glucose regulation, may explain hypercortisolism in MDD and T2D, at least in a subgroup of patients." (PMID 38927393, 2024). "In conclusion, CRHR1- and CRHR2-risk variants might confer pleiotropic effects, some specific to PCOS, and some related to hypercortisolism, T2D, and MDD." (PMID 37543650, 2023).
bipolar disorder (2 papers, 2022). A disorder of the brain that causes unusual shifts in mood, energy, activity levels and the ability to carry out day-to-day tasks. "CRHR2 variants have also been reported in patients with bipolar disorder (rs8192492-risk allele-A), PTSD (rs2267715-risk allele-A), and T2D (rs917195 T2D-risk allele-C); and certain haplotypes have been associated with suicidal risk in bipolar patients." (PMID 36077219, 2022). "The corticotropin-releasing hormone receptor 2 (CRHR2) gene and suicidality in bipolar disorder have previously been studied." (PMID 36817247, 2022).
Hepatic steatosis (2 papers, 2018 to 2020). Steatosis is a term used to denote lipid accumulation within hepatocytes. "Male mice with Crhr2 genotype showed microvesicular hepatic steatosis on chow diet as well as on a fatty diet." (PMID 30400826, 2018).
Infertility (2 papers, 2013 to 2021). "Our findings point to a new inflammatory modulator pathway in which CRH, UCN, CRHR1 and CRHR2 are involved acting by an autocrine/paracrine pathway in eutopic and ectopic endometrium potentially affecting the pathogenesis of this benign disease and infertility profile of endometriotic women." (PMID 23638035, 2013).
ovarian tumors (2 papers, 2007 to 2018). "In summary, we found that CRH, its receptors CRHR1 and CRHR2, and the proapoptotic molecule FasL are produced by human ovarian tumour cells in situ." (PMID 17667919, 2007).
viral infection (2 papers, 2014 to 2021). "For example, over half of these genes have been previously associated with viral infection or replication, or have been found to physically interact with viral proteins (e.g. CLDN3; CRHR2; ILF2; ILF3; LTF; miR-122; RCHY1; and, RUVBL2)." (PMID 25079789, 2014).
adenoma (1 paper, 2021). A neoplasm arising from the epithelium. "However, the mRNA levels of these tumor-associated genes were similar between the adenomas from Apcmin/+; Crhr2−/−, Apcmin/+; Crhr2+/−, and Apcmin/+; Crhr2+/+ mice." (PMID 33494263, 2021). "Conversely, the percentage proportion of large adenomas was markedly increased in the intestine of Apcmin/+; Crhr2−/− mice compared to those of littermate Apcmin/+; Crhr2+/− and Apcmin/+; Crhr2+/+ mice." (PMID 33494263, 2021). "However, the number of adenomas was dramatically increased in the colon of Crhr2−/− mice compared to that of Crhr2+/+ mice." (PMID 33494263, 2021). "Accordingly, the histological analysis exhibited that either Crhr1 or Crhr2 deletion does not alter the histopathological nature of adenomas developed in Apcmin/+ mice." (PMID 33494263, 2021).
gestational diabetes (1 paper, 2020). Carbohydrate intolerance first diagnosed during pregnancy. "Blocking the endogenous CRHR2 agonist during gestation induces a mild glucose intolerance rather than overt gestational diabetes suggesting that UCN2 may act in concert with other placental signals to fine-tune the compensatory β-cell adaptations to maternal insulin resistance during pregnancy." (PMID 32106091, 2020).
Glucose intolerance (1 paper, 2020). Glucose intolerance (GI) can be defined as dysglycemia that comprises both prediabetes and diabetes. "The pharmacological blockade of CRHR2 signalling during pregnancy appears to reveal a transient and mild glucose intolerance in comparison to the more profound defect in glucose tolerance displayed by mutant PRLR mice." (PMID 32106091, 2020).
heroin addiction (1 paper, 2018). "Hypothesis-driven study of variants in stress-related genes and heroin addiction identified an association with non-coding SNP in the CRHR2 gene." (PMID 29953524, 2018). "In our previous studies of stress-related genes that included samples that overlap the samples used in the current study, we have reported associations of variants in FKBP5, GAL, CRHR2, and AVPR1A with heroin addiction." (PMID 29953524, 2018).
intestinal tumor (1 paper, 2021). "However, these protein levels, indicative of protein-losing enteropathy in mice with intestinal tumors, were markedly reduced in Crhr2−/− mice compared to those of Crhr2+/+ mice." (PMID 33494263, 2021).
lichen (1 paper, 2024). "Immunohistochemical expression of CRH, urocortin (UCN), FasL and their receptors CRHR1, CRHR2 and Fas was studied in vulvar tissue sections obtained from patients with histologically confirmed diagnosis of lichen, vulvar intraepithelial neoplasia (VIN) and vulvar squamous cell carcinoma (VSCC)." (PMID 37382757, 2024). "In the present retrospective study, we investigated the immunohistochemical expression of CRH, UCN, FAS-L and of their receptors CRHR1, CRHR2 and FAS, on paraffin-embedded tissue samples from patients diagnosed with lichen (sclerosus or planus), VIN or VSCC." (PMID 37382757, 2024).
lung carcinoma (1 paper, 2022). "Results showed that the signature based on MAS1L, TCP10L2, and CRHR2 is a useful tool to predict prognosis and lung cancer lymph node metastasis." (PMID 36277017, 2022).
necrotizing enterocolitis (1 paper, 2017). Necrotizing enterocolitis (NEC) is a devastating disease that affects mostly the intestine of premature infants. "Thus, selectively blocking CRHR1 and promoting CRHR2 activity could prevent the development of intestinal injuries and enhance repair in the neonatal period when there is increased risk of intestinal injury such as necrotizing enterocolitis." (PMID 28492284, 2017).
ovarian carcinoma (1 paper, 2007). A malignant neoplasm originating from the surface ovarian epithelium. "Here, we examined immunohistochemically the expression of CRH, CRHR1, CRHR2 and FasL in 47 human ovarian cancer cases." (PMID 17667919, 2007). "In the present study, we examined the distribution of CRH, CRHR1, CRHR2 and FasL peptides in ovarian carcinoma and we investigated the potential role of CRH and FasL in modulating the immune defenses of ovarian cancer cells." (PMID 17667919, 2007).
pancreatitis (1 paper, 2020). Inflammation of the pancreas. "In male mice lacking a function CRF2 receptor (Crhr2-/-), pancreatitis causes severe and more dramatic distortion of RER cisternae, mitochondrial swelling, and unusual autophagic bodies compared to C57BL6 mice of both sexes as well as Crhr2-/- female mice." (PMID 32244319, 2020).